CCDC97 (coiled-coil domain containing 97)
Description:
May play a role pre-mRNA splicing through the association with the splicing factor SF3B complex which is involved in branch-site recognition.
Synonyms: FLJ40267; MGC20255
Tractability: PROTAC: ubiquitination databases record sites on it; its protein half-life has been measured.
Gene: Protein-coding gene on chromosome 19 (41,310,172 to 41,324,873, forward strand). Ensembl gene ENSG00000142039.
Subcellular location: Nucleus
Subcellular location (Human Protein Atlas): Nucleoplasm; Cytosol; Plasma membrane
Gene Ontology:
Cellular component: nucleoplasm; nucleus
Genetic constraint (gnomAD): Loss-of-function variants: 25 observed, 30.39 expected, observed/expected ratio (o/e) 0.82, 90% interval 0.6 to 1.15. The upper end of that interval is the gene's LOEUF score, 1.15, which puts it in group 5 of 6, group 1 being the genes least tolerant of losing a copy. Missense variants: 403 observed, 467.09 expected, observed/expected ratio (o/e) 0.86, 90% interval 0.79 to 0.94. Synonymous variants: 212 observed, 193.39 expected, observed/expected ratio (o/e) 1.1, 90% interval 0.98 to 1.23.
Homologues: Orthologues: macaque CCDC97 (99% identical), chimpanzee CCDC97 (98% identical), dog CCDC97 (90% identical), guinea pig CCDC97 (90% identical), rabbit CCDC97 (87% identical), rat Ccdc97 (83% identical), mouse Ccdc97 (83% identical), pig CCDC97 (71% identical), zebrafish ccdc97 (44% identical), tropical clawed frog ccdc97 (43% identical), Drosophila melanogaster CG7810 (26% identical), Caenorhabditis elegans R10D12.13 (25% identical).
Diseases named in the same sentence as CCDC97 in open-access papers:
CCDC97 is named in the same sentence as 5 diseases in open-access papers, as found by Europe PMC text mining. Sharing a sentence is not in itself a finding about the gene and the disease. The quoted sentences say what the papers report.
coronary artery disease (1 paper, 2024). "CCDC97 and CCDC107 were found to be associated with coronary artery disease and diabetes-associated atherogenesis, respectively." (PMID 38540995, 2024).
cancer (1 paper, 2021). A tumor composed of atypical neoplastic, often pleomorphic cells that invade other tissues. "Regarding the mechanisms of DYRK1B on cancer progression, silencing DYRK1B consistently reduced two rare genes, CCDC97 and ZNF581, the physiological functions of which have not been previously reported." (PMID 34830933, 2021).
tumor (1 paper, 2021). "CCDC97 and ZNF581 were positively correlated with DYRK1B expression and might be involved in DYRK1B-mediated tumor malignancy in TNBC patients, providing DYRK1B as a potential theranostic target for TNBC." (PMID 34830933, 2021).
CCDC97 also shares sentences with these, for which no sentence is quoted: atherosclerosis (1 paper); diabetes (1).